PER2 (period circadian regulator 2)
Diseases named in the same sentence as PER2 in open-access papers (continued):
Sharing a sentence is not in itself a finding about the gene and the disease.
social phobia (1 paper, 2010). An anxiety disorder characterized by an intense, irrational fear of one or more social or performance situations in which the individual believes that he or she will be scrutinized by others. "Interestingly, there is a functional partnership between ARNTL2 and PER2 that might bridge social phobia and alcohol use to end in high alcohol intake." (PMID 20180986, 2010).
status epilepticus (1 paper, 2018). Status epilepticus is defined as a continuous seizure lasting more than 30 min, or two or more seizures without full recovery of consciousness between any of them. "In this study, we systematically evaluated the temporal expression of seven core circadian transcripts (Bmal1, Clock, Cry1, Cry2, Per1, Per2, and Per3) and the spontaneous locomotor activity (SLA) in post-status epilepticus (SE) model of mTLE." (PMID 30116220, 2018).
substance abuse (1 paper, 2017). The use of a drug for a reason other than which it was intended or in a manner or in quantities other than directed. "It remains to be determined whether the expression of this gene specifically in astrocytes can play a role in vivo, since it has been shown that PER2 does modify circadian sleep cycle during sleep disruptions and also in substance abuse." (PMID 28279172, 2017).
thyroid (1 paper, 2021). "The expression levels of CLOCK, BMAL1 and PER2 in thyroid malignant group were significantly higher than benign and normal groups, while CRY2 was decreased, p < 0.05." (PMID 34211057, 2021). "We then chose CLOCK, BMAL1, CRY1, CRY2, PER1 and PER2 to observe the changes of circadian rhythm genes in thyroid malignant tissues." (PMID 34211057, 2021).
tongue cancer (1 paper, 2016). A malignant neoplasm affecting the tongue. "Of interest, the expression of key clock genes was either down-regulated, e.g., BMAL1, CLOCK, PER1, PER2, and PER3, or up-regulated, e.g. CYR1 and CRY2, in tongue cancer samples in relative to that in normal control samples." (PMID 27079271, 2016).
vitamin D deficiency (1 paper, 2011). A nutritional condition produced by a deficiency of VITAMIN D in the diet, insufficient production of vitamin D in the skin, inadequate absorption of vitamin D from the diet, or abnormal conversion of vitamin D to its bioactive metabolites. "The primary molecular target of NPAS2 is Per2, which was also found to be significantly modulated by vitamin D deficiency in the peri-implant tissue." (PMID 21264318, 2011). "Among the VD-deficiency altered-gene list, we found Neuronal PAS domain 2 (NPAS2) and Period Homolog 2 (Per2) as the most significantly affected genes by vitamin D deficiency in the peri-implant tissue." (PMID 21264318, 2011). "NPAS2 and Aryl hydrocarbon receptor nuclear translocator-like (ARNTL/Bmal 1) were upregulated around implant and diminished by vitamin D deficiency, whereas the expression pattern of Per2 was complementary." (PMID 21264318, 2011). "On the contrary, the cluster containing Per2 was upregulated by vitamin D deficiency and showed a complementary expression pattern to the NPAS2 cluster." (PMID 21264318, 2011).
ZIKV infection (1 paper, 2018). "Among the other temporally regulated genes in ZIKV infection, is the circadian clock gene PER2 that resembles HSPA5." (PMID 29451494, 2018).
tumor (194 papers, 2010 to 2026). "In mice, this downregulation of PER2 is further associated with increased levels of Cyclin D and Cyclin E, as well as accelerated tumour growth in vivo." (PMID 39413708, 2024). "PER2 is implicated in the modulation of DNA damage-responsive pathways, thereby mitigating tumor initiation." (PMID 38607733, 2024). "In mice, Per1 and Per2 were identified as tumor suppressors, while PER2-deficient animals had an increased risk of genetic and UV-induced cancer." (PMID 39519024, 2024). "Melatonin demonstrates upregulation of mRNA levels of Clock, and Per2, and downregulation of Bmal1 mRNA, thereby suggesting a protective effect on rhythm loss during tumor progression." (PMID 39012661, 2024). "Per2 mutant mice exhibit increased cancer susceptibility and altered tumour responses post-γ radiation." (PMID 39566400, 2024). "Mice were subcutaneously injected with Per2-deficient or control GH3 cells to induce a xenograft tumor." (PMID 37215573, 2023). "Loss of Per2 in mice decreased the growth rate of transplanted GH3 tumor, and protected from estrogen-induced PRLPA." (PMID 37215573, 2023). "We found that deficiency of Per2 retarded the growth of the GH3 tumor as revealed by reduced tumor volume and tumor mass as well as a lower plasma GH level." (PMID 37215573, 2023). "PER2 and other core circadian rhythm genes form a transcription-translation feedback loop; abnormal transcription and translation cause tumor proliferation, metastasis, and invasion." (PMID 38074100, 2023). "Depleted PER2 has been implicated to impair normal behavior and circadian rhythm, which also significantly increases tumor incidence and proliferation of abnormal phenotypes." (PMID 35606376, 2022). "One example is two noncoding variants within the PER2 enhancer that have tumor suppressive properties in AML and are potentially controlled by the nuclear receptor program." (PMID 33117405, 2020). "Which of these cell types contributes to the observed inhibitory effect of Per2 loss on tumor growth and metastasis?" (PMID 33123539, 2020). "Here, we showed that loss of PER2 enhanced tumor invasion by activating transcriptional genes of EMT, including TWIST1/2, ZEB1/2, and MMP1, suggesting a wide-range influence of PER2 on EMT process." (PMID 32185221, 2020). "Loss of Per2, however, rearranges the premetastatic liver niche, in a manner that activates tumor suppressing pathways in response to the presence of cancer cells, resulting in attenuated metastatic spread." (PMID 33123539, 2020). "The pathway-based analysis further revealed that four tumor suppressor genes (Per2, Prkaa2, Npas2, Arntl) were associated with circadian rhythm pathway." (PMID 31523185, 2019). "Further, genetic ablation of both Per1 and Per2 caused an arrhythmic phenotype together with premature aging conditions, e.g., early decline in fertility, kyphosis and predisposed tumor incidences." (PMID 28108951, 2017). "Inactivation of Per2 caused deregulation of Bmal1 expression which contributed to a high incidence of tumor formation." (PMID 27492458, 2016). "We found that tumor growth in the Per2-deficient group was substantially faster than the control virus-treated group or the blank-treated group (both, P < 0.05)." (PMID 27036047, 2016). "Per2-deficient mice have a low tumor incidence; however, following γ-irradiation, these mice become cancer-prone." (PMID 27036047, 2016).
tumor (continued). "In mice, Per2 loss-of-function mutations exhibit higher tumour incidence and show greater susceptibility to radiation-induced malignant lymphoma compared with wild type." (PMID 27590298, 2016). "Knocking out or mutating Per2 increases cancer cell growth, and accelerates spontaneous and carcinogen-induced tumor development in rodents." (PMID 26544624, 2015). "The Per2 gene functions in tumor suppression by regulating DNA-damage-responsive pathways, and Per2-deficient mice show signs of premature aging and increased neoplastic tissue development following gamma irradiation." (PMID 25333958, 2014). "Mutation of the key circadian gene Per2 has been found to influence tumor development in the ApcMin/+ mouse model, supporting a role for neurobiology in oncogenesis." (PMID 25288683, 2014). "Per2-deficient mice showed a marked increase in tumor development and reduced apoptosis in thymocytes following γ-radiation." (PMID 22935435, 2012). "A study using a genetically engineered mouse model has proved that genetic loss of Per2 or Bmal1, which play cell-autonomous tumor-suppressive roles in transformation and lung tumor progression, leads to increased c-Myc expression and promotes lung tumorigenesis." (PMID 40040723, 2025). "Conversely, Per2 deficiency disrupts tumour suppressors (Ccnd1 and c-Myc), promoting tumour growth." (PMID 39566400, 2024). "Interestingly, members of the Per subfamily act as tumor suppressor genes in mice, and the downregulation and loss of PER2 is associated with tumor proliferation and metastasis, including NSCLC." (PMID 37264412, 2023). "However, Fu’s7 research showed that Per2 deficient mice were enhanced sensitivity to radiation associated tumor development causing lowered animal survival in Per2 deficient mice." (PMID 36465103, 2022). "Downregulation of per2 was associated with tumour progression in non-small cell lung cancer." (PMID 36361993, 2022). "Lower PER2 levels were significantly associated with tumor multiplicity (p = 0.02)." (PMID 36284088, 2022). "Similar to that observed for PER1, PER2 expression was associated with effectiveness in radiotherapy, again supporting the hypothesis that both genes are tumor suppressors." (PMID 34361055, 2021). "Another team also found that knocking out two genes, Bmal1 and Per2, caused tumours to grow faster." (PMID 31744421, 2019). "Per2 mutation severely deregulated liver gene or protein expressions related to three cancer hallmarks, including uncontrolled proliferation, genomic instability, and tumor promoting inflammation, and accelerated liver carcinogenesis several-fold." (PMID 27494874, 2016). "Thus, the specific core clock genes Per2 and Per1 are considered as tumor suppressors linked to tumor numbers and cancer growth rates." (PMID 26541675, 2015). "In murine models, Per2 mutations result in temporal changes in mRNA expression for genes associated with cell cycle regulation and tumor suppression, including c-Myc, cyclins and mouse double minute 2 homolog, resulting in an impaired DNA damage response and accelerated tumor growth." (PMID 25360177, 2014). "Furthermore, Per2 has tumor-suppressor properties and is often mutated or downregulated in human breast cancers." (PMID 25333958, 2014). "Similarly, the circadian clock gene PER2 is closely linked to tumor suppression." (PMID 40243466, 2025). "In addition, mice deficient in Per2 showed an increase in tumor formation after ɣ-radiation." (PMID 27492458, 2016).
tumor (continued). "Tumor growth, gene expression of Per1, Per2, Per3, and Rev-Erbα, and TNF-α concentrations were analyzed at six circadian time points." (PMID 41736190, 2026). "Scheduled exercise at ZT2 significantly increased the amplitude of Per2, Per3, and Rev-Erbα expression rhythms in tumor tissue." (PMID 41736190, 2026). "Taken together, all these results suggest that metformin upregulates PER2, inhibits transplanted xenograft tumor growth in nude mice by inhibiting the SIRT2/G6PD signaling pathway and enhances radiotherapy sensitivity." (PMID 40166471, 2025). "Despite the promising results of the current study supporting the tumor-suppressive role of PER2 in HCC, the main limitation of this study is that it was conducted in a single HCC cell model." (PMID 40521302, 2025). "Remarkably, the results of the present study showed that the cytoplasmic PER2 localization was associated with increased MDM2 overexpression, further confirming MDM2 as a marker of tumor aggressiveness and drug resistance." (PMID 40521302, 2025). "This work involved using real-time luciferase reporters of Per2 and Bmal1 to characterize the circadian clock in various tumor cell lines." (PMID 40133704, 2025). "KDM6A-pSer829 suppressed PER2 expression via histone modification, increased glycolytic activity, and enhanced tumor proliferation." (PMID 41184251, 2025). "Integrated chromatin profiling and metabolic analyses revealed that phosphorylated KDM6A-pSer829 drives glycolytic reprogramming through H3K27Me3-dependent transcriptional silencing of PER2, ultimately promoting tumor growth in vitro and in vivo." (PMID 41184251, 2025). "The anti-tumor effect of ATF3 inducer 1-targeted upregulation of PER2 combined with copper ionophore elesclomol (ES) was found to be significantly enhanced compared with that of monotherapy in an OSCC xenograft model." (PMID 40113747, 2025). "Studies have reported a lack of tumor suppression and cell cycle disorders in mice with Per2 gene defects, suggesting that Per2 plays a tumor-suppressive role through the DNA damage response pathway." (PMID 38903177, 2024). "Choroid plexus tumours exhibit hypermethylated promoter regions of PER2, correlating with significantly lower PER2 expression." (PMID 39413708, 2024). "The finding showed that theloss of BMAL1 and Per2 further increased tumor burden and decreasedsurvival, which comparatively had a greater impact in the BMAL1-mutated group." (PMID 39072055, 2024). "Overexpression and downregulation of PER2 in osteosarcoma cells have been shown to reduce proliferation and induce apoptosis in tumour cells, respectively, as well as affected tumour cell migration." (PMID 38336976, 2024). "The promotion of cancer cell growth in vitro and the enhancement of time-dependent tumor growth in vivo occur exclusively during specific periods of the day, as a result of the downregulation of either Per1 or Per2." (PMID 39012661, 2024). "Irradiation was shown to induce different clock proteins: PER2 was induced by irradiation to promote DNA damage and apoptosis, and PER2 KD reduced the radiosensitivity of tumours in vivo using an U343 mouse model." (PMID 38378853, 2024). "Expression of the clock genes cry2 and per2 showed a more pronounced decrease in tumours compared to adjacent healthy tissue in males than in females." (PMID 37831728, 2023). "Overall, these findings supported a critical role of PER2 in regulation of pituitary cell cycle and tumor growth." (PMID 37215573, 2023).
tumor (continued). "SR8278 (50 mg/kg) was intraperitoneally injected into GH3 xenograft tumor-bearing mice at ZT14 (corresponding to a peak PER2 expression) for 10 days." (PMID 37215573, 2023). "In brief, the clock gene is closely related to substance metabolism, and PER2 plays a critical role in tumor growth and metabolism." (PMID 37069338, 2023). "The tumour oncogenic role is usually attributed to the cry1 gene, whereas per2 is recognized as a tumour suppressor." (PMID 37831728, 2023). "Early studies by other members of our team have shown that the clock gene PER2 can inhibit the proliferation of tumor cells." (PMID 37069338, 2023). "The circadian clock gene Per2 has been suggested to lead to c‐Myc overexpression and an increased tumor incidence." (PMID 36806631, 2023). "Given the broad application of immune checkpoint inhibitors in anti-tumor treatment, we studied the relationship between PER2 expression and immunosuppression checkpoints." (PMID 38074100, 2023). "Low expression of PER2 protein in HCC tissues correlated with tumor diameter, portal invasion, TNM staging, and outcomes in HCC patients." (PMID 38074100, 2023). "Per1-/-, Per2-/-, Cry1-/-, Cry2-/- andBmal1-/- mice presented with increased spontaneous and radiation-induced tumor development." (PMID 39282509, 2023). "The expression of BMAL1, CLOCK, Rev-Erbα, and PER2 in intraperitoneal macrophages regulated the expression levels of F4/80 and CD11c in tumor tissues." (PMID 35116071, 2022). "PER2 has also been shown to operate both as a tumor suppressor as well as an important facilitator of the DDR." (PMID 35163264, 2022). "Immunohistochemistry in non-tumor thyroids revealed that PER2 protein levels were significantly reduced in samples over the age of 60 (p = 0.04)." (PMID 36284088, 2022). "In murine models, PER2 was necessary for the radiation-induced upregulation of clock gene proteins that resulted in better tumor suppression and survival." (PMID 35163264, 2022). "Previously, we observed downregulation of cry2 and per2 expression in tumour tissue in comparison to adjacent tissue, and higher expression of cry1 in right-sided tumours but not in left-sided tumours compared to surrounding tissue." (PMID 36361993, 2022). "The expression levels of CUL1, NR1D1, and PER2 were lower in tumor deletion samples than in other tumor and normal tissue samples." (PMID 36439444, 2022). "Hypoxia leaded to the activation of EMT genes, including TWIST1, SLUG and SNAIL, by degrading PER2, which was considered to be a tumor suppressor, and disrupting the PER2 repression complex." (PMID 36226050, 2022). "Overexpression of PER1 and PER2 in PCa cell growth suppression occurs via apoptosis, suggesting that Per 1-2 exerts anti-tumor effects." (PMID 36291899, 2022). "For instance, PER1 and PER2 proteins have already been described as tumor suppressors in cancer cell cultures, as well in animal experiments." (PMID 35897788, 2022). "Given the proposed role of per2 as a tumor suppressor gene we next investigated the contribution of the per2 gene to the circadian regulation of the cell cycle in zebrafish." (PMID 34539343, 2021). "The expression of the Per2 gene in the early and mid of the light or dark phase determines the wax and wane in tumor size." (PMID 35126099, 2021). "The expression levels and circadian oscillation of Clock and Per2 mRNA were disrupted in 4T1 tumor bearing mice." (PMID 33890571, 2021). "Silencing PER2 in melanoma cells reduces the apoptosis of tumor cells and induces tumor development in an in vitro experiment." (PMID 34069297, 2021).